FBN2 (fibrillin 2)
Description:
[Fibrillin-2]: Fibrillins are structural components of 10-12 nm extracellular calcium-binding microfibrils, which occur either in association with elastin or in elastin-free bundles. Fibrillin-2-containing microfibrils regulate the early process of elastic fiber assembly. Regulates osteoblast maturation by controlling TGF-beta bioavailability and calibrating TGF-beta and BMP levels, respectively. [Placensin]: Hormone secreted by trophoblasts that promotes trophoblast invasiveness. Has glucogenic activity: is able to increase plasma glucose levels (By similarity).
Synonyms: DA9; CCA; EOMD
Tractability: Antibody: UniProt places it where antibodies can reach, with high confidence; its Gene Ontology location is reachable by antibodies, with high confidence; UniProt predicts a signal peptide or a membrane-spanning region. PROTAC: ubiquitination databases record sites on it.
Gene: Protein-coding gene on chromosome 5 (128,257,909 to 128,659,185, reverse strand). Ensembl gene ENSG00000138829.
Subcellular location: Secreted; Secreted, extracellular space, extracellular matrix (Fibrillin-2); Secreted (Placensin)
Subcellular location (Human Protein Atlas): Cytosol; Nucleoplasm; Primary cilium; Predicted to be secreted
Pathways (Reactome):
Extracellular matrix organization: Degradation of the extracellular matrix; Elastic fibre formation; Molecules associated with elastic fibres
Gene Ontology:
Molecular function: protein binding; extracellular matrix constituent conferring elasticity; extracellular matrix structural constituent; hormone activity; calcium ion binding
Biological process: camera-type eye development; embryonic eye morphogenesis; bone trabecula formation; glucose homeostasis; glucose metabolic process; negative regulation of transforming growth factor beta receptor signaling pathway; positive regulation of bone mineralization; positive regulation of osteoblast differentiation; signal transduction
Cellular component: extracellular matrix; extracellular region; microfibril; non-collagenous component of interstitial matrix
Genetic constraint (gnomAD): Loss-of-function variants: 83 observed, 318.9 expected, observed/expected ratio (o/e) 0.26, 90% interval 0.22 to 0.31. The upper end of that interval is the gene's LOEUF score, 0.31, which puts it in group 1 of 6, group 1 being the genes least tolerant of losing a copy. Missense variants: 2,963 observed, 3,496.5 expected, observed/expected ratio (o/e) 0.85, 90% interval 0.82 to 0.87. Synonymous variants: 1,226 observed, 1,227.5 expected, observed/expected ratio (o/e) 1, 90% interval 0.95 to 1.05.
Gene-disease validity (ClinGen):
ClinGen rates the evidence that FBN2 causes each of these diseases.
congenital contractural arachnodactyly (autosomal dominant): Definitive. Congenital contractural arachnodactyly (CCA, Beals syndrome) is a connective tissue disorder characterized by multiple flexion contractures, arachnodactyly, severe kyphoscoliosis, abnormal pinnae and muscular hypoplasia.
Homologues: Orthologues: chimpanzee FBN2 (99% identical), macaque FBN2 (99% identical), pig FBN2 (98% identical), dog FBN2 (98% identical), mouse Fbn2 (96% identical), rabbit FBN2 (96% identical), rat Fbn2 (96% identical), guinea pig FBN2 (93% identical), tropical clawed frog fbn2 (84% identical), zebrafish fbn2a (62% identical). Paralogues in human: FBN1 (68% identical), FBN3 (65% identical).
Diseases named in the same sentence as FBN2 in open-access papers:
FBN2 is named in the same sentence as 122 diseases in open-access papers, as found by Europe PMC text mining. Sharing a sentence is not in itself a finding about the gene and the disease. The quoted sentences say what the papers report.
congenital contractural arachnodactyly (41 papers, 2006 to 2026). "A missense heterozygous paternally inherited variant in FBN2 gene has been diagnosed in a female patient, presenting with relevant joint and skin laxity, pectus excavatum, arachnodactyly, and scoliosis." (PMID 41010011, 2025). "The FBN2 gene is causative for the congenital contractual arachnodactyly also known as Beals syndrome, a connective tissue disorder clinically overlapping with Marfan syndrome but differing for the presence of joint contractures and “crumpled ears”." (PMID 41010011, 2025). "Impaired assembly plays a role in the molecular pathogenesis of genetic disorders caused by mutations in Fibrillin-1 (Marfan syndrome) and Fibrillin-2 (congenital contractural arachnodactyly)." (PMID 39273357, 2024). "In human patients, mutations in FBN2 lead to congenital contractural arachnodactyly (CCA), or Beals–Hecht syndrome, an autosomal dominant disorder with features that partially overlap with MFS." (PMID 39768188, 2024). "We note that FBN2 is specifically associated with congenital contractural arachnodactyly, i.e., a particularly tall long-limbed phenotype, with long slender fingers and toes." (PMID 38656999, 2024). "Heterozygous pathogenic variants in FBN2 have been associated with congenital contractual arachnodactyly." (PMID 39098944, 2024). "Variants in FBN2 encoding fibrillin-2 cause congenital contractural arachnodactyly and mouse models for this condition have also been produced." (PMID 37972149, 2024). "It was considered to be pathogenic as parental segregation revealed it to be de novo in P1; this private FBN2 variant confirmed a diagnosis of congenital contractual arachnodactyly in P1." (PMID 39098944, 2024). "In summary, whole‐exome sequencing was used to detect the c.3344A>T (D1115V) mutation in the FBN2 gene of a Chinese family with Congenital Contractual Arachnodactyly." (PMID 33638605, 2021). "FBN2 intragenic deletions or splice site mutations have been published on some occasions associated with contractural congenital arachnodactyly." (PMID 34356068, 2021). "Fbn2 mutations in mice show syndactyly, while FBN2 mutations in humans are associated with congenital contractual arachnodactyly (OMIM 121050)." (PMID 31637260, 2019). "DA9, Beals syndrome, has also been found to be a collagen disorder with a mutation in the fibrillin FBN2 gene." (PMID 26537820, 2015). "The cognate region of FBN2 is the most commonly mutated in Beal syndrome and would plausibly be associated with a similar dominant negative effect." (PMID 24348270, 2013). "Beals syndrome has distinct features however, and is caused by a mutation in the fibrillin-2 gene (FBN2) in 5q23, while Marfan syndrome is caused by mutations in fibrillin-1." (PMID 16740166, 2006). "Mutations in FBN2 codifying for Fibrillin 2 protein were discovered to cause Beals syndrome." (PMID 37443678, 2023). "Missense variants in FBN2 are known to cause congenital contractual arachnodactyly." (PMID 36800380, 2023). "Mutations in the fibrillin genes cause alterations in elastogenesis and connective tissue disorder conditions, such as Marfan syndrome or Weill-Marchesani syndrome if mutations occur in the FBN1 gene, or congenital contractural arachnodactyly (Beals syndrome) if the FBN2 gene is altered." (PMID 34945227, 2021). "In other words, a missense mutation in the FBN2 gene, which leads to the folding destabilization and reduced structural integrity of fibrillin-2, may cause the muscle defects underlying contractural arachnodactyly." (PMID 28379158, 2017). "The FBN2 gene is the causative gene for Congenital Contractural Arachnodactyly (CCA, OMIM:121050), inherited in an autosomal dominant manner with near-complete penetrance." (PMID 41146935, 2025). "Mutations in the FBN2 gene are closely related to hereditary connective tissue diseases, such as congenital contractural arachnodactyly (CCA), macular degeneration (MD), and myopathy, etc.." (PMID 39474271, 2024).
congenital contractural arachnodactyly (continued). "Congenital contractural arachnodactyly (CCA) is a rare autosomal dominant condition caused by mutations in the fibrillin 2 gene (FBN2) Prenatal diagnosis and counselling' were carried out simultaneously to avoid the birth of the sick fetus." (PMID 33638605, 2021). "Congenital contractural arachnodactyly (CCA) or Beals-Hecht syndrome is a rare autosomal dominant connective tissue disease; it is associated with the disease-causing fibrillin-2 (FBN2) gene." (PMID 35126451, 2021). "Congenital contractural arachnodactyly (CCA) is a rare autosomal dominant condition caused by mutations in the fibrillin 2 gene (FBN2)." (PMID 33638605, 2021). "We identified a novel heterozygous mutation (c.4177T>G and p.Cys1393Gly) in FBN2 that cosegregated with congenital contractural arachnodactyly (CCA) in a five-generation Chinese family." (PMID 30147916, 2018). "Mutations in the gene for fibrillin-2 (FBN2) cause congenital contractural arachnodactyly (CCA) or Beals syndrome (now designated as Distal Arthrogryposis, Type 9, OMIM #121050), a dominantly inherited disorder of connective tissue." (PMID 26114882, 2015). "Mutations in the gene coding for fibrillin-2 (FBN2), an ECM glycoprotein, cause Congenital contractural arachnodactyly." (PMID 35177651, 2022). "Marfan syndrome (MFS) and congenital contractural arachnodactyly were the first diseases to be linked to the human FBN1 and FBN2 genes, respectively, which encode the fibrillin-1 and fibrillin-2 isoforms." (PMID 24035709, 2013). "Two such connective tissue disorders are Marfan's syndrome and Congenital Contractural Arachnodactyly (CCA), which are caused by dominant mutations in the fibrillin-1 (FBN1) and fibrillin-2 (FBN2) genes respectively." (PMID 20161761, 2010). "Genetic variants in genes including TGFBR1, TGFBR2, TGFB2, TGFB3, SMAD2, and SMAD3 result in Loeys–Dietz syndrome and are reported to cause Marfan-like phenotypes and variants in FBN2 and COL3A1 result in congenital contractural arachnodactyly and Ehlers–Danlos syndrome type IV." (PMID 38791509, 2024). "The FBN2 variant causes Beals syndrome (Congenital contractual arachnodactyly) (MIM:121050), which is characterized by arachnodactyly and camptodactyly; The ANKRD11 mutation causes KBG syndrome, which may contribute to the ASD in this patient." (PMID 35346302, 2022). "Variants in FBN2 have been reported to associated with congenital contractural arachnodactyly (CCA) and early-onset macular degeneration (MD), whereas the proband's mother and sister who carried the heterozygous missense variant (c.2432T>C, p.I811T) in FBN2 didn't have any phenotypes of CCA or MD." (PMID 33748123, 2021). "The gene FBN2 has high similarity to FBN1; as a result, pathogenic variants in FBN2 have been reported to cause a phenotypically related disorder termed congenital contractual arachnodactyly (CCA) (MIM:121050), which also presents with Marfanoid body habitus and arachnodactyly." (PMID 38791509, 2024). "Fibrillin-1 and fibrillin-2, encoded by FBN1 and FBN2, respectively, play significant roles in elastic fiber assembly, with pathogenic variants causing a diverse group of connective tissue disorders such as Marfan syndrome (MFS) and congenital contractural arachnodactyly (CCD)." (PMID 38791509, 2024). "Heterozygous mutations in fibrillin-1 or fibrillin-2 cause two clinically related disorders of the connective tissue, MFS (OMIM 154700) and congenital contractural arachnodactyly (CCA: OMIM 121050) respectively." (PMID 21126338, 2010). "Marfan's syndrome and congenital contractural arachnodactyly (CCA) result from dominant mutations in the genes FBN1 and FBN2 respectively." (PMID 20161761, 2010). "The patient however did not have any clinical features of Beal syndrome, a FBN2-related disorder." (PMID 39669619, 2024).
Marfan syndrome (22 papers, 2006 to 2026). A disorder of the connective tissue. "Fibrillin 2 (FBN2) was first discovered while studying Marfan syndrome, and its encoded products are associated with elastin fibres." (PMID 37337404, 2023). "Genetic testing revealed a variation in the FBN2 gene 253 (c.6583C > T), supporting the diagnosis of variant Marfan syndrome." (PMID 38099230, 2023). "Although FBN1 mutations play a central role in the clinical manifestations of Marfan syndrome, fibrillin-2 (FBN2) mutations have also been shown to potentially cause the disease." (PMID 37332582, 2023). "Genetic testing identified a heterozygous mutation (c.6583C > T) in the FBN2, supporting the diagnosis of variant Marfan syndrome." (PMID 38099230, 2023). "Familial genetic testing revealed a heterozygous mutation (c.6583C > T) in FBN2, supporting the diagnosis of a variant of Marfan syndrome." (PMID 38099230, 2023). "Among numerous gene mutations affecting the skeleton, FBN1 and FBN2 mutations cause Marfan syndrome and congenital contractural arachnodactyly, respectively, in humans." (PMID 35503090, 2022). "Mutations in the gene for fibrillin-1 cause the Marfan syndrome, while mutations in the gene for fibrillin-2 cause Congenital Contractural Arachnodactyly." (PMID 26114882, 2015). "FBN2 mutations are responsible for many cases of CCA while mutation of the related gene FBN1 can result in Marfan's syndrome." (PMID 20161761, 2010). "Gene targeting in embryonic stem cells has been used to generate null alleles of Fbn1 and Fbn2 and both have proven to be partial but imperfect models of Marfan's syndrome and CCA respectively." (PMID 20161761, 2010). "FBN2 loss-of-function causes musculoskeletal features of Marfan syndrome." (PMID 39063061, 2024). "Mutations in FBN3 as well as in two other family members of the fibrillin-family FBN1 and FBN2 have been identified in several disorders, including Bardet–Biedl syndrome and Marfan syndrome." (PMID 41440000, 2025). "Severe cardiovascular manifestations, especially aortic root and ascending aorta aneurysms, which are potentially lethal, as well as ocular manifestations, occur frequently in Marfan syndrome, but neither is typically associated with FBN2 mutations." (PMID 35503090, 2022). "Many genes encoding collagen, Timps and other proteins known to be involved in connective tissue diseases such as EDS and Marfan syndrome, including Adamts2, Fbn1 and Fbn2, had more than a 4-fold decreased expression in Zeb2-cKO fibroblasts compared with wild-type fibroblasts." (PMID 28422173, 2017). "Fbn1-null mutants do display the vascular abnormalities that have been associated with Marfan's syndrome but they do not appear to manifest most other symptoms seen in humans with the condition, while reported Fbn2-null mutants do not fully recapitulate the CCA phenotype." (PMID 20161761, 2010). "Given that muscular weakness and muscular atrophy are common findings in patients suffering from Marfan's syndrome and CCA, Fbn2-null mice may be a good model for investigating this aspect of the disease further." (PMID 20161761, 2010).
macular degeneration (6 papers, 2016 to 2024). Loss of vision in the central portion of the retina (macula), secondary to retinal degeneration. "Rare and common variants in FBN2 can contribute to Mendelian and complex forms of macular degeneration." (PMID 37100863, 2023). "One non-USH proband exhibited variants in different genes underlying HI (MYH14) and retinal or macular degeneration (FBN2)." (PMID 34148116, 2022). "Diseases including MFS with aortopathy, talipes, equinovarus, macular degeneration, and scoliosis could also be triggered by a pathogenic variant in FBN2." (PMID 38791509, 2024). "The findings may provide new insights for the understanding of molecular mechanism of fbn2-deficiency retinopathy in particular and for the etiology of macular degeneration in general, and they may be helpful for the development of new drugs for the treatment of inherited retinal degenerations." (PMID 37100863, 2023). "Emerging evidence suggests that alterations in specific genes encoding ECM proteins (TIMP3, CTRP5, FBN2, and FBLN 1–6) are implicated in macular degeneration." (PMID 27007659, 2016). "In eight sporadic cases, we detected eight heterozygous rare sequence variants in six macular degeneration genes (CFH; FBLN1, OMIM 135820; FBLN3/EFEMP1, OMIM 601548; FBLN5, OMIM 604580; HMCN1, OMIM 608548; FBN2, OMIM 612570)." (PMID 27007659, 2016).
colorectal cancer (5 papers, 2014 to 2023). A primary or metastatic malignant neoplasm that affects the colon or rectum. "Previous studies have found that FBN2 harbour cancer-specific promoter methylation in human colorectal cancer." (PMID 35991839, 2022). "In a further study, the Fibrillin-2 (FBN2) gene was determined to be hypermethylated in colorectal cancer tissue." (PMID 29038612, 2017). "According to clinical studies, 63% of patients with primary colorectal cancer had the FBN2 gene methylated in their tumour samples; this suggests that FBN2 may be a novel diagnostic for the hepatic metastases of colorectal cancer." (PMID 37337404, 2023). "Hypermethylation of FBN2 has been previously reported in RCC (34%) as well as several other cancer types including small cell lung cancer, esophageal squamous cell carcinoma and colorectal cancer, in which it was potentially associated with hepatic metastasis." (PMID 24454902, 2014). "Furthermore, clinical research has found that FBN2 gene methylation exhibited in 63% of tumor samples of patients with primary colorectal carcinoma, and FBN2 might be an early and frequent event in precancerous and cancerous lesions of the colon and rectum." (PMID 35991839, 2022). "FBN2 plays a role in the ERK signaling pathway and its DNA hypermethylation was recently discussed as a biomarker for colorectal cancer." (PMID 32727620, 2020).
scoliosis (5 papers, 2021 to 2025). A congenital or acquired spinal deformity characterized by lateral curvature of the spine. "FBN1, FBN2, and variants near SOX9, and KCNJ2 are associated with severe scoliosis (greater than 40 degrees)." (PMID 39781499, 2025). "Rare mutations in FBN1 and FBN2 were associated with scoliosis, even though these scoliosis patients do not have typical features consistent with the syndromic condition." (PMID 34356049, 2021).
breast carcinoma (4 papers, 2017 to 2022). "A total of three key genes were obtained after overlapping the predicted target genes with the differentially upregulated genes in the four types of breast cancer: FBN2, MEX3A, and TPD52." (PMID 35433464, 2022). "Human bone marrow mesenchymal stem cell-derived exosomes inhibited the growth of breast cancer cells and promoted the expression of FBN2, MEX3A, and TPD52 by transporting miR-139-5p." (PMID 35433464, 2022). "Their expression and prognosis in the four types of breast cancer were observed separately, and the results showed that FBN2, MEX3A, and TPD52 were more expressed in luminal A, HER2, and TPD52 than in normal samples." (PMID 35433464, 2022). "In contrast, FBN2 was found to be upregulated in different molecular subtypes of breast cancer in the present study, and this result, although different from the findings of previous studies, gives rise to the idea to study the role of FBN2 in a deeper way." (PMID 35433464, 2022). "Additionally, aberrant methylation of FBN2 has been observed in breast cancer, non-small cell lung cancer, and esophageal squamous cell carcinoma; FBN2 methylation might negatively impact STS prognosis as well." (PMID 32084007, 2020). "The target genes of miR-139-5p were predicted by using an online database TargetScan and miRDB, and three key genes, FBN2, MEX3A, and TPD52, were screened in combination with differentially expressed genes in different molecular subtypes of breast cancer." (PMID 35433464, 2022). "The results showed that FBN2, MEX3A, and TPD52 were highly expressed in luminal A, luminal B, HER2-enriched, and basal-like breast cancers compared with normal samples." (PMID 35433464, 2022). "In addition, the key target genes of miR-139-5p, FBN2, MEX3A, and TPD52 also provide potential targets for personalized treatment of different molecular subtypes of breast cancer." (PMID 35433464, 2022).